IL6 (interleukin 6)
Diseases named in the same sentence as IL6 in open-access papers (continued):
Sharing a sentence is not in itself a finding about the gene and the disease.
Insulin resistance (continued). "Several studies have indicated that interleukin-6, primarily produced in adipose tissue, acts as a significant factor in WBC differentiation and is linked to insulin resistance." (PMID 38957446, 2024). "Adipose cells, especially those belonging to visceral fat, release pro-inflammatory cytokines such as TNF-α or IL-6 and adipokines such as leptin, which promote insulin resistance and inflammation." (PMID 38999756, 2024). "Leptin-1 also increased serum adiponectin and decreased serum TNF-α and IL-6 level signifying the improvement in insulin-sensitivity and decrease in insulin-resistance, respectively in db/db mice." (PMID 39490585, 2024). "Previous research indicates that levels of tumor necrosis factor (TNF), interleukin (IL)-1, and IL-6 are elevated in AS and contribute to the onset of insulin resistance." (PMID 39649224, 2024). "Conversely, sustained elevated levels of IL-6, induced by the introduction of IL-6, lead to insulin resistance and decreased body mass." (PMID 39596226, 2024). "Research has established that VAT contributes to metabolic dysregulation, primarily through its role in insulin resistance and the secretion of various inflammatory factors, including interleukin-6 (IL-6) and C-reactive protein (CRP)." (PMID 39319256, 2024). "The accumulation of TG in adipocytes can lead to a rise in resistin, TNF-α, and interleukin 6, which can result in insulin resistance." (PMID 38867151, 2024). "Pioglitazone exhibits various anti-inflammatory activities, including the significant reduction of IL-6 and tumor necrosis factor α in individuals with insulin resistance." (PMID 38932215, 2024). "Previously, elevated circulating levels of IL-6 were considered an independent predictive factor for T2DM and were associated with the development of inflammation, insulin resistance, and β-cell dysfunction." (PMID 39235859, 2024). "The peripheral actions of leptin consist of the upregulating proinflammatory cytokines such as tumor necrosis factor-α and interleukin-6 (IL-6), mediators that play an important role in the pathogenesis of type 2 DM and insulin resistance." (PMID 38707092, 2024). "In the metabolically active organs, IL-6-mediated STAT3 activation destabilizes insulin receptor substrate 1 (IRS1) protein, causing insulin resistance." (PMID 38474057, 2024). "Leptin, adiponectin, and resistin are key markers, along with pro-inflammatory cytokines like TNFα, IL-1β, and IL-6, which also play roles in insulin resistance." (PMID 39407941, 2024). "Irregular production of IL-6 and long-term exposure lead to inflammation, which induces insulin resistance and overt T2DM." (PMID 39051061, 2024). "IL-6 interferes with insulin signaling, contributing to insulin resistance and metabolic disorders related to glucose and lipid metabolism." (PMID 39691364, 2024). "According to previous studies, fatty liver affects gastric carcinogenesis through enhanced insulin resistance; chronic inflammation with various signaling pathways, such as IL-6 and TNFα; adipocytokines; or alteration of gut microbiota." (PMID 38804394, 2024). "Normally, NF-κB and JNK, as well as the inflammatory factor interleukin-6 (IL-6), mediate insulin resistance." (PMID 39539361, 2024). "TNF-α impairs insulin action by activating JNK and IKKβ pathways, disrupting insulin signaling, while IL-1β and IL-6 exacerbate insulin resistance by inhibiting receptor functions and glucose uptake." (PMID 39458518, 2024). "Increased levels of IL-1β, IL-6, and TNF-α have been observed in adipose tissue and serum of obese patients, which is associated with insulin resistance in humans and obese mice exposed to HFD." (PMID 39274918, 2024). "Research indicates that the METS-IR index is positively correlated with levels of inflammatory markers like CRP and IL-6, suggesting that higher insulin resistance corresponds to stronger inflammatory responses." (PMID 39514584, 2024).
Insulin resistance (continued). "As adipocytes expand, immune cells, particularly macrophages, infiltrate the adipose tissue and secrete pro-inflammatory cytokines such as TNF-α and IL-6, which play a key role in the development of insulin resistance." (PMID 39700087, 2024). "By linking inflammation, oxidative stress, and insulin resistance, IL-6 plays a central role in diabetic pathology, making it a potential target for therapeutic interventions aiming to reduce ROS and inflammation in diabetic patients." (PMID 39857603, 2024). "Inflammatory factors such as IL-6 induce insulin resistance by enhancing serine/threonine phosphorylation of insulin receptor substrate-1 (IRS-1)." (PMID 38529045, 2024). "TNF-α stimulates IL-1b and IL-6 and increases insulin resistance by phosphorylating insulin receptors." (PMID 39597886, 2024). "The immune-inflammatory mediators, such as TNF-α, IL-1, and IL-6, can lead to insulin resistance due to oxidative stress from high glucose intake, reduce insulin sensitivity, and produce high levels of these mediators in the bloodstream." (PMID 39199338, 2024). "Inflammatory cytokines released by hepatic adipose tissue, such as tumor necrosis factor-alpha (TNF-α) and interleukin-6 (IL-6), can impair insulin signaling pathways, leading to insulin resistance." (PMID 39683601, 2024). "In the context of insulin resistance, IL-6 interferes with insulin signaling pathways by activating serine kinases, such as c-Jun N-terminal kinase (JNK), which phosphorylate insulin receptor substrate proteins and disrupt insulin receptor signaling." (PMID 38044678, 2024). "Increases in inflammatory factors, such as tumor necrosis factor-alpha and interleukin 6, can further exacerbate insulin resistance, promoting thrombosis and atherosclerosis." (PMID 39744244, 2024). "Studies also show that chronic hepatic exposure to IL-6 promotes gluconeogenesis and insulin resistance." (PMID 39766906, 2024). "Interleukin-6 (IL-6) has many functions and is potentially involved in the onset of insulin resistance." (PMID 39456928, 2024). "Previous research has demonstrated a positive correlation between IL-6 levels and systemic insulin resistance, IL-6 expression in the liver, liver inflammation, and the degree of fibrosis in patients with NAFLD." (PMID 38732626, 2024). "TLRs stimulate NFKB and JNK signaling, which also lead to upregulation of the expression of inflammatory cytokines including TNFα and IL6, and further induce insulin resistance in adipocytes and macrophages." (PMID 39264906, 2024). "These cytokines, encompassing TNF, IL-6, and IL-1β, can potentially induce insulin resistance in the originating tissues like the liver and adipose tissue." (PMID 38004353, 2023). "Of note, adipose-derived TNF-α and IL-6 are crucial adipokines that suppress adipocyte insulin sensitivity and even lead to insulin resistance by attenuating insulin receptor-substrate 1 (IRS-1), which is a necessary component of insulin signaling." (PMID 37555019, 2023). "Increased levels of systemic IL-6 are a strong predictor of T2D and are thought to have a role in the development of inflammation, insulin resistance, and β-cell dysfunction." (PMID 36677559, 2023). "Such a manifestation finds its roots in the heightened activity of TRAF2/IL-6, culminating in the facilitation of IL-6/leptin-driven Th17 cellular formation and subsequent insulin resistance within adipose frameworks." (PMID 38035065, 2023). "It has been found that resistin levels show a positive correlation with fat mass, insulin resistance, and interleukin 6 (IL-6)." (PMID 37763771, 2023). "An increased IL-6 level was an independent predictor of type 2 diabetes and played an important role in inflammation, insulin resistance, and beta-cell dysfunction." (PMID 36769452, 2023).
Insulin resistance (continued). "Accumulated visceral adipose tissue produces more inflammatory cytokines, such as tumor necrosis factor alpha (TNF-a), interleukin-6 (IL-6) and IL-1b, and less adiponectin, which induces systemic insulin resistance." (PMID 37895151, 2023). "Socs3 can be induced by certain inflammatory cytokines (e.g., TNFα and IL6) to contribute to inflammation-mediated insulin resistance in the liver and adipose tissue." (PMID 36709676, 2023). "Increased levels of systemic IL-6 is a strong predictor of T2D and is shown to have a role in the development of inflammation, insulin resistance, and beta cell dysfunction." (PMID 36672202, 2023). "Adipose tissue-resident macrophages release interleukin-6, which is contributed to insulin resistance in PCOS21." (PMID 37355686, 2023). "In the early stages of MAFLD, macrophages secrete pro-inflammatory cytokines such as TNF-α and IL-6, which contribute to liver injury and promote the development of insulin resistance." (PMID 37361209, 2023). "For example, overexpression of IL-6 in white adipose tissue has been shown to promote insulin resistance and glucose intolerance in mice." (PMID 37238961, 2023). "Various studies found a significant link between COVID-19 disease and the overexpression of Interleukin-6 (IL-6), while the immune response mediated by IL-6 can induce insulin resistance and injury and apoptosis of pancreatic β-cells." (PMID 37286981, 2023). "The cytokine impairs glucose and insulin metabolism in young diabetic mice and increases the production of IL-6, which induces insulin resistance." (PMID 36768715, 2023). "Phenols, a large class of bioactive molecules, are important for the modulation of T2D and insulin resistance due to their ability to reduce pro-inflammatory cytokines, such as interleukin-1β (IL-1β), interleukin-6 (IL-6), and tumor necrosis factor-α (TNF-α)." (PMID 37108509, 2023). "In the liver and adipose tissue, IL-6 induces insulin resistance due to insulin receptor inhibition and enhances inflammation." (PMID 37894792, 2023). "CRP is stimulated by IL-1β, TNF-α and IL-6 in the liver, which act together to activate serine and threonine kinases to suppress insulin signal transduction and thus promote insulin resistance." (PMID 37891561, 2023). "Hesperidin was investigated for its potential to mitigate insulin resistance induced by IL-6 in hepatocytes." (PMID 38234970, 2023). "It inhibits the production of cytokines that induce insulin resistance, such as tumor-necrosis factor or IL-6." (PMID 36768715, 2023). "IL-6 promotes insulin resistance through multiple mechanisms, and NASH severity, fibrosis stage, and insulin resistance are associated." (PMID 37007030, 2023). "These recruited M1 macrophages secrete pro-inflammatory cytokines, including TNF, IL-6, and IL-1β, and oxidative metabolites such as superoxide and nitric oxide (NO), resulting in inflammation and insulin resistance." (PMID 36838843, 2023). "Increased levels of inflammatory markers (IL-6 and TNF-α) in the body are associated with an increased risk of insulin resistance and cardiovascular disease." (PMID 36976940, 2023). "H. pylori infection increases the incidence of diabetes due to its increased levels of C-reactive protein and interleukin 6 (IL-6), which results in insulin resistance." (PMID 37700268, 2023). "In this research paper, we aim to review the role of skeletal muscle-derived IL-6 in lipid metabolism and other physiological activities, such as insulin resistance and glucose tolerance." (PMID 37555019, 2023). "Muscle fibers also influence the immunological response by controlling interleukin-6 and other peptides, regulating the synthesis of tumor necrosis factor-alpha and insulin resistance." (PMID 37592262, 2023). "miR-146a expression was shown to be negatively correlated with glycated hemoglobin, insulin resistance, NF-κB mRNA levels and circulating levels of TNFα as well as IL-6." (PMID 37629307, 2023).
Insulin resistance (continued). "Previous studies have reported that IL-6 can promote glucagon secretion and induce insulin resistance." (PMID 36769472, 2023). "The presence of carotid plaque and cIMT and the insulin resistance indices were unrelated to IL-6 after multivariate adjustment." (PMID 37762312, 2023). "In conclusion, hesperidin remarkably ameliorates hepatic insulin resistance induced by IL-6 in hepatocytes." (PMID 38234970, 2023). "It interacts with inflammatory signaling pathways, such as NF-κB and JNK, regulating the production of pro-inflammatory cytokines like TNF-α and IL-6, which contribute to chronic inflammation and insulin resistance." (PMID 37605113, 2023). "Studies have shown that decreased levels of adiponectin and increased levels of inflammatory cytokines like IL-6, and TNFα contribute directly to insulin resistance and also directly prevent adiponectin secretion from adipocytes." (PMID 37013538, 2023). "Several pro-inflammatory cytokines, such as the C-reactive protein (CRP), tumor necrosis factor-α (TNF-α) and interleukin-6 (IL-6), have been unequivocally shown to promote both insulin resistance (IR) and atherogenesis." (PMID 36900073, 2023). "Another functionof IL-6 is that it can contribute to the development of insulin resistance, a keyfactor in the pathogenesis of type 2 diabetes." (PMID 39077574, 2023). "On the contrary, pro-inflammatory cytokines from adipose tissue, such as TNF-α, IL-6, and MCP-1, are known to be associated with insulin resistance." (PMID 36834930, 2023). "In the liver, IL-6 antagonizes insulin signaling and induces inflammation, which after reaching a certain threshold, leads to insulin resistance and non-alcoholic fatty liver disease." (PMID 37664841, 2023). "The reduction in adipose tissue decreases the release of proinflammatory adipokines, such as tumor necrosis factor-alpha (TNF-α) and interleukin-6 (IL-6), which contribute to a low-grade systemic inflammation and insulin resistance." (PMID 38201924, 2023). "Several investigations have found in murine and cell-based studies that IL-6 signaling for more than 24 h induces insulin resistance in adipose and hepatic tissue." (PMID 37593740, 2023). "IL-6 is known to contribute to hyperglycemia through insulin resistance, and multiple retrospective analyses have reported that hyperglycemia is associated with adverse outcomes." (PMID 37693502, 2023). "Several reports have revealed that inflammatory molecules such as interleukin 6 (IL-6), tumor necrosis factor-α (TNF-α), and C-reactive protein (CRP) are elevated in individuals with T2DM and associated with insulin resistance." (PMID 37445656, 2023). "Inflammation and insulin resistance are closely linked, and inflammatory cytokines such as TNF-α, IL-6, IL-1 and IL-8 can inhibit insulin signaling by multiple mechanisms." (PMID 36860845, 2023). "A study found that the insulin resistance of mice was significantly improved after the application of neutralizing IL-6 antibody." (PMID 38239743, 2023). "Inflammatory cytokines, such as tumor necrosis factor-alpha (TNF-α) and interleukin-6 (IL-6), can potentially hinder insulin signaling in renal cells, resulting in insulin resistance." (PMID 37868469, 2023). "IL-6 has also been indicated in the facilitation of ketogenesis through induction of cellular insulin resistance in hepatocytes." (PMID 37102024, 2023). "Wunderlich and others have shown the involvement of SOCS1 and SOCS3 in insulin resistance through the elevation of interleukin-6 (IL-6), thus leading to the activation of the JAK-STAT pathway." (PMID 37529379, 2023). "FGF23 is associated with inflammation through IL-6 (interleukin 6), IL-10 (interleukin 10), and CRP (C-reactive protein) and with symptoms of metabolic syndrome: insulin resistance, visceral obesity, and dyslipidemia." (PMID 38139126, 2023).
Insulin resistance (continued). "In this line, its endothelial overexpression can delay lipid accumulation and insulin resistance development in obese transgenic mice by inducing the secretion of IL-6 followed by the expression of thermogenic and lipolytic genes." (PMID 36905456, 2023). "The role of IL-6 in inflammation in insulin target tissues, the pathogenesis of systemic insulin resistance, and increasing vascular permeability contributing to tissue damage have been reported." (PMID 37685858, 2023). "Elevated levels of IL-6 have beenassociated with impaired insulin signaling and glucose uptake in tissues,potentially leading to insulin resistance and glucose intolerance." (PMID 39077574, 2023). "Insulin resistance can also induce adipose tissue inflammation to activate and release proinflammatory cytokines such as IL-6 and TNF-α, which induce endothelial dysfunction, leading to albuminuria and impaired renal function." (PMID 37680883, 2023). "A high-fat diet induced hepatic insulin resistance and marked increases in plasma TNFα (eight-fold) and IL-6 (60%) in apo-CIII-overexpressing mice." (PMID 37895151, 2023). "For example, interleukin 6, leptin and tumour necrosis factor α take part in not only insulin resistance but also inflammation and other physiological processes." (PMID 37029402, 2023). "IL-6 is a proinflammatory cytokine that is involved in the immune response and plays a role in insulin resistance." (PMID 37238961, 2023). "Key players that were found to be involved in insulin resistance are inflammatory cytokines like TNFα, IL-6, C-reactive protein and plasminogen activator inhibitor, all of which were found to be elevated in obese mice." (PMID 38137918, 2023). "This review discusses the role of pro-inflammatory cytokines, particularly Interleukin-6, tumor necrosis factor-α, and interleukin-8, play a significant role in the induction of insulin resistance in adipose cells." (PMID 38259415, 2023). "While hepatic and adipose tissue production of IL-6 is believed to contribute to insulin resistance, its generation in skeletal muscle, particularly during intense exercise, is considered advantageous." (PMID 38004353, 2023). "miR-146a expression is negatively correlated with HbA1C, TRAF6 mRNA, TNF, IL-6 and insulin resistance." (PMID 37786444, 2023). "Overexpression of PTPN2 significantly reduces the levels of NF-κB, TNF-α, IL-6, and the inflammatory response in diabetic mice, and then alleviated insulin resistance." (PMID 37670950, 2023). "As depicted in this review, in insulin resistance, there is an increase in pro-inflammatory cytokines such as interleukin (IL)-1, IL-6, and tumor necrosis factor (TNF)-α and ROS." (PMID 37629193, 2023). "Genistein suppresses NF-κB activation, reduces TNF-α and IL-6 production, and reactivates insulin-mediated Akt and endothelial NO synthase phosphorylation to improve insulin resistance-related endothelial dysfunction." (PMID 37229273, 2023). "The activation of JNK can further activate the transcriptional regulator AP-1 and induce the expression of inflammatory genes, such as IL-6 and TNF, inhibiting insulin signaling and causing insulin resistance." (PMID 36875140, 2023). "Such link between IL-6 and VFL was expected in our study, since IL-6 is released to the circulation from visceral adipose tissue rather from subcutaneous, contributing to inflammation and insulin resistance." (PMID 37529617, 2023). "High-level endotoxemia has been found to increase TNF-α and IL-6 concentrations and insulin resistance." (PMID 37009872, 2023). "The increase of proinflammatory cytokine IL-6 after surgery is related to insulin resistance, and its sensitivity is higher than CRP." (PMID 37928355, 2023). "IL-6 induces insulin resistance by downregulating insulin receptor substrate-1 (IRS-1) phosphorylation and transcription and by upregulating suppressor of cytokine signaling 3 (SOCS3), which inhibits insulin receptors." (PMID 37893164, 2023).